CD44 (CD44 molecule (IN blood group))
Diseases named in the same sentence as CD44 in open-access papers (continued):
Sharing a sentence is not in itself a finding about the gene and the disease.
tumor (continued). "The interaction of HA and CD44 was found to promote epidermal growth factor receptor (EGFR)-mediated pathways in different tumor entities, in turn leading to tumor cell proliferation and survival via mitogen-activated protein kinase (MAPK) and phosphoinositide 3-kinase (PI3K)/AKT activation." (PMID 31052565, 2019). "In addition, research has proposed that HAS2 affects hyaluronic acid synthesis as a result of HA/CD44 signaling pathway activation to influence tumor microenvironment transformation." (PMID 31109321, 2019). "However, L-selectin controls other aspects of T cell activation as shown by increased numbers of CD44+ CD27+ “central memory” F5LΔP cells in the lungs of tumor bearing mice as well as Ki67 expression and altered proliferation ex vivo." (PMID 31249570, 2019). "CD44 is a multifunctional, transmembrane glycoprotein that was first defined as a lymphocyte homing receptor expressed in embryonic stem cells, hematopoietic stem cells, and tumor stem cells." (PMID 31301090, 2019). "More importantly, FACS analysis for the CD44-CD24 markers revealed that administration of the LSD1 inhibitor resulted in a significant reduction in the number of tumor CSCs (CD44+CD24-/low), compared to tumors before treatment initiation and to vehicle-treated ones." (PMID 31627418, 2019). "CD44 has multiple ligands, which contribute to tumor progression." (PMID 31921628, 2019). "We hypothesized that aberrant methylation in the HCC cells mediated by dysregulated NNMT may alter m6A abundance in the CD44 mRNA, thereby increasing the proportion of CD44V3 splice variant in these cells and accelerating tumor progression." (PMID 31294922, 2019). "From the GEPIA analysis, the mRNA levels of these factors were slightly downregulated in tumor tissues compared with those in normal tissues, which indicated that posttranslational modification plays crucial roles in CD44 and CTTN expression." (PMID 30832692, 2019). "Thus, LMW-HA/CD44/RHAMM binding promotes angiogenic capillary invasion into the tumor microenvironment." (PMID 31134064, 2019). "CD44 can also facilitate the arrest of circulating tumor cells prior to extravasation." (PMID 31623163, 2019). "During HA/CD44-mediated signaling process, Twist phosphorylated by c-Src is also able to interact with miR-10 promoter (with E-box domain) and activates the onset of miR-10b gene expression/production and tumor cell-specific activities in cancer cells." (PMID 31293964, 2019). "The expression of CD44 in HCC is associated with poor prognosis and tumor aggressiveness." (PMID 30858465, 2019). "Importantly, this approach was shown to eliminate CD44+ CSCs-like cells leading to a significant reduction in tumour growth." (PMID 31835751, 2019). "CD44 staining of tumor cells was seen in 26 of 30 pre-chemotherapy samples." (PMID 30999901, 2019). "However, the interaction between CD44 and HA seems to play an important role in promoting cytoskeleton rearrangement through RhoA activation and Ca2+ mobilization that increases tumor cell migration and invasion." (PMID 31052565, 2019). "The presence of CD90-positive and CD44-positive cells was found to correlate with tumor metastasis." (PMID 31547062, 2019). "Additionally, the leg tumor treated with radiation and anti-PD-L1 had higher CD44+ expression on CD8 + CD3+ cytotoxic T cells compared to untreated control tumors." (PMID 31412954, 2019). "CD44 is a surface glycoprotein to promote tumor cell motility." (PMID 30874545, 2019). "Furthermore, tumor sphere formations of CD44+ PDAC cells were inhibited in the presence of 50 μg/mL BRM270." (PMID 31049070, 2019). "Thus, it appears that CD44 is involved in morphogenesis, wound healing, and tumor progression as an extracellular matrix for cell movement." (PMID 30478679, 2019).
tumor (continued). "This review focuses first on matrix HA interaction with CD44 in regulating cancer cell signaling pathways, and then describes downstream target functions of these signaling events that contribute to tumor initiation, migration, invasion, chemoresistance, and tumor progression." (PMID 31293964, 2019). "Some studies suggest that expression of total CD44 may be correlated with distant metastasis, tumor recurrence and a worse prognosis." (PMID 30788285, 2019). "Moreover, the sulfation pattern of CS on versican appears to be critical for interaction with L-selectin, P-selectin, and CD44, molecules involved in endothelial cell adhesion and/or tumor angiogenesis." (PMID 31195728, 2019). "Further investigation confirmed variable expression of CD44 also in primary tumours." (PMID 31477698, 2019). "Moreover, degradation of HA to smaller oligosaccharides by hyaluronidases is reported to induce cleaving of CD-44 in the tumor microenvironment, leading to tumor progression, as seen in breast, ovarian, glioma, and colon cancers." (PMID 31013618, 2019). "Deciphering the molecular mechanisms highlighted the TGIF1 loss-induced activation of the hyaluronan synthase 2 (HAS2)-CD44 signaling pathway and upregulation of the immune checkpoint regulator PD-L1 to facilitate the epithelial–mesenchymal transition (EMT) and tumor immune suppression." (PMID 31109321, 2019). "Therefore, it is feasible to use either LncRNA UCA1 si treatment and/or ROCK inhibitor to limit tumor cell migration and invasion and to reduce HA/CD44-induced tumor metastasis and progression." (PMID 31293964, 2019). "CD44, a receptor for the extracellular matrix polysaccharide hyaluronate, is involved in several physiological processes—including intercellular adhesion, cell-matrix adhesion, and cell migration—as well as tumor cell invasion and metastasis." (PMID 31569404, 2019). "Furthermore, they showed the tumor accumulation thanks to the CD44 targeting: an improved in vitro uptake of HepG2 cells was observed by fluorescence of the targeted liposome compare to the unconjugated one." (PMID 35582577, 2019). "Moreover, both Notch and CD44 have been implicated in hypoxia-driven enrichment of CSC population, tumour recurrence and enhanced metastatic phenotype after treatment with anti-angiogenic agents or hypoxia inducible factors." (PMID 30975104, 2019). "Signal of activity was defined as a ≥20% reduction of CSC (defined by either the ALDH+ or CD24−/CD44+ phenotype) in tumor tissue from baseline values as measured by flow cytometry accompanied by a consistent reduction of the same cell population by immunohistochemistry (IHC)." (PMID 30788286, 2019). "More importantly, blocking STn-MUC1 and CD44 glycoforms partially reverted DC maturation, suggesting that targeting STn-expressing glycoproteins may allow circumventing tumor-induced tolerogenic mechanisms." (PMID 31157165, 2019). "Based on our previously published work we have established that the FKBPL pre-clinical peptide, AD-01, could inhibit both endothelial and tumour cell migration in a CD44-dependent manner." (PMID 30975104, 2019). "In addition, CD44 expression almost statistically significantly correlated with PD-L1 expression and with a trend can inverse correlation to tumor infiltrating pro-inflammatory immune effector cells." (PMID 31741714, 2019). "In addition, although a body of literature supports a role for CD44 in metastasis, there are also data describing an inhibitory effect of CD44 on tumor metastasis." (PMID 31762938, 2019). "To verify it, we detected the HO8910 CD44+CD117+ CSC subpopulation in xenograft tumor tissues." (PMID 31008116, 2019). "Furthermore, HPPD nanoparticles also slightly enhanced the antitumor efficacy of DOX, which should be ascribed to their efficient tumor-accumulation through the EPR and CD44-mediated active tumor targeting." (PMID 31623608, 2019).
tumor (continued). "The tumor growth of MDA-MB-468 co-grafts with 3T3HAS3 CD44 KO T1 and T2 was slightly reduced when compared with MDA-MB-468 + 3T3HAS3 co-grafts (at last data point analyzed, the average tumor sizes of T1 and T2 co-grafts were 82.2% and 76.4% of MDA-MB-468 + 3T3HAS3 co-grafts, respectively)." (PMID 31762938, 2019). "The transmembrane glycoprotein receptor cluster of differentiation 44 (CD44) binds to various cell surface ligands and enables cell‐to‐cell and cell‐to‐matrix adhesion, which is essential for tumor cell metastasis and progression." (PMID 31294922, 2019). "Indeed, treatment of ApcMin/þ mice with celecoxib, the prostaglandin-endoperoxide synthase 2 selective inhibitor, or the EP4 receptor (prostaglandin receptor) antagonist ONOAE-208 resulted in a reduction of tumor CD133+CD44+ cells and tumor burden." (PMID 30967773, 2019). "It lessens articulation of CD44 on the surface of tumor cells." (PMID 31554850, 2019). "Cisplatin treatment could restore the splenic immunophenotype downregulating CD44+, IL-17A+ MDSCs presumably because of the smaller tumor burden, on the other hand MDSCs are also sensitive to low dose chemotherapy due to their high proliferative potential." (PMID 31881770, 2019). "There is a positive correlation between CD44 expression and tumor metastasis." (PMID 29540668, 2018). "CD44 is a major cell matrix-associated protein whose expression has been correlated with enhanced tumor aggressiveness, metastasis and lack of response to a variety of therapies." (PMID 29899840, 2018). "However, we did not detect the increase in the number of memory T cells including effector (CD44+ CD62L−) or central memory (CD44+ CD62L+) T cells in all tumor-free mice in the current study." (PMID 29954062, 2018). "To determine whether the CHI3L1/CD44 axis governs GC cell metastasis in vivo, we evaluated experimental lung metastasis after lateral tail vein injection of tumor cells." (PMID 30165890, 2018). "However, due to the weak binding ability of hyaluronan oligosaccharide to CD44, targeting for tumor drug delivery has been restricted." (PMID 29899207, 2018). "Increased expression of the SR proteins is also associated with an increased complexity of CD44 isoforms, indicating increased SR protein expression that may promote alternative splicing of CD44 mRNA and contribute to tumor progression." (PMID 29483847, 2018). "GCSCs have also been identified using specific markers, such as CD44; the stemness properties of GCSCs are studied using two standard approaches: the in vitro sphere-forming assay and in vivo serial tumor passaging." (PMID 28284008, 2018). "Given the putative role of CSCs in tumour development and recurrence, we suppose that the low doxorubicin sensitivity of BrCCh1 cells that originated from the recurrent tumour is caused by CSC-like CD44+/CD24− cells." (PMID 29986702, 2018). "Notably, by the impact of uPAR on integrin activity and the association of CD44 with integrins, a concomitant blockade of MMP and uPAR exerts an additive effect in prohibiting tumor cell migration." (PMID 30211160, 2018). "In these cell line models, CD44 promotes tumor cell proliferation and cell survival." (PMID 29747682, 2018). "However, there was a significant increase in the numbers of the CD44+ cells in the hypoxic (EGFP+) MCF7 tumor cell population with the predominant increase of the CD44+/CD24+ population." (PMID 29510720, 2018). "CD44 is a cell surface glycoprotein that is involved in multiple cellular functions relevant to the immune system including lymphocyte activation, recirculation and homing, hematopoiesis, and tumor metastasis." (PMID 29375724, 2018). "On the other hand, a high level of VEGF in the tumor periphery may suppress the invasive activity of CD44." (PMID 30210550, 2018). "Interestingly, combinatorial effect of 5FU+ Silibinin demonstrated significant reduction in the number and size of tumor spheres formed by HCT116 derived CD44+ subpopulation compared to untreated cells." (PMID 30451890, 2018).
tumor (continued). "In our material, expression of CD44 was localized around perivascular areas in tumor tissues." (PMID 29914429, 2018). "For example, knockdown of the HA receptor CD44 in MSCs blocks both their ability to be recruited to the tumor site, and their tumor promoting functions Recent studies have identified CAF properties that are distinct from activation of normal fibroblasts responding-to-wounding." (PMID 29868579, 2018). "Inhibition of CD44-HA interaction results in abrogation of tumor cell motility." (PMID 29747682, 2018). "CD44+/CD133+ double-positive cells grow typical tumor spheres." (PMID 29747682, 2018). "CD44+/24-/low tumor cells ≥1% was considered positive as previously reported." (PMID 29423076, 2018). "Similar results were obtained for CD44 positive tumor cells and CD166 positive cells." (PMID 29547583, 2018). "Sorting through the functional roles of CD44 isoforms is complicated by the finding that tumor cells may express multiple CD44v isoforms and that these are found in different levels of expression." (PMID 29747682, 2018). "CD44 can undergo isoform switching in tumor cells as demonstrated by Brown and colleagues." (PMID 29747682, 2018). "To investigate the existence and biological functions of GSCs expressing CD44 in the tumor periphery of GBM, we tried to establish stem-like cells by placing the cells in primary culture from the tumor tissues in the tumor periphery in neural stem cell culture medium." (PMID 30210550, 2018). "However, it is known that Salmonella treatment leads to the downregulation of CD44, a key cell surface molecule on Tregs as well as tumor cells, and contributes to tumor angiogenic invasiveness and proliferative potential." (PMID 29765907, 2018). "Moreover, in subcutaneous implantation nude mice models, 5 Aza induced a higher inhibition rate on tumor growth of CD133+/CD44+ cells with high-OPN compared with the low-OPN controls." (PMID 30064482, 2018). "As reported, in aggressive tumors, overexpression of CD44 might help tumor cells adhere to extracellular matrix and facilitate the formation of VMs." (PMID 29378465, 2018). "The charge-reversible property would enable sPEG to shield cationic HA/CSO-SS-Hex/Fe3O4/GA core at physiological pH, but switch to positive charge in acidic tumor microenvironment and shed off to re-expose HA for CD44 tumor cell targeted and promoting GA delivery." (PMID 30334478, 2018). "While FDG could not reveal any difference in receptor expression between the treated and untreated mice, 124I-AbD19384 successfully identified the tumours with high expression of CD44." (PMID 30149561, 2018). "The tumor-derived HA oligosaccharides enhance CD44 intracellular cleavage and tumor cell motility." (PMID 29747682, 2018). "The role of CD44 in promoting tumor invasion may be mediated in part by this binding proteolytically active MMP-9 at the membrane." (PMID 29747682, 2018). "Thus, to assess if ICG-001 inhibited the ability of CD44+CD24highCD29+ cells to drive rapid OSCC tumor growth and metastases, we adapted an embryonic zebrafish xenograft model to screen for aggressive human stem cell-like OSCC cells." (PMID 30029671, 2018). "Furthermore, tumor‐suppressive miRNAs, including miR‐451a,39 miR‐15a,40 and miR‐363,41 were hypermethylated and down‐regulated in EpCAM+/CD44+ GC cells." (PMID 29862663, 2018). "During tumor progression, deregulated activation of Aurora A kinase (AURKA) is functionally linked to epithelial-to-mesenchymal transition (EMT) reprogramming and expansion of a subpopulation of tumor-initiating cells harboring a CD44+/CD24low/− phenotype." (PMID 29289986, 2018). "In each case, CD44 expression was confirmed by central reviewing of tumour biopsies." (PMID 29356983, 2018).
tumor (continued). "The functional cytosensor uses HA receptor protein CD44 as a target to capture specific tumor cells (HCT-116) and has satisfactory performance of improved immobilization capacity for cells, as well as good biocompatibility for preserving the activity of immobilized living cells." (PMID 30567299, 2018). "Additionally, we confirmed CD44 expression in tumor endothelial cells from A2780 tumor tissues and compared it with the CD44 expression in the corpus luteum of mouse ovary." (PMID 29890852, 2018). "CD44 proteins regulate growth, survival, differentiation and migration and may be therefore involved in tumor progression and metastasis." (PMID 29652830, 2018). "To identify tumor‐suppressive miRNAs repressed by DNA hypermethylation in highly tumorigenic GC, we isolated EpCAM+/CD44+ GC cells from primary GC tumor tissues and performed methyl‐CpG‐binding domain (MBD) sequencing (MBD‐seq) and miRNA sequencing (miRNA‐seq)." (PMID 29862663, 2018). "In addition, CD44 positivity was dramatically higher in the differentiated tumor areas of T3 compared to T1 and T2, and it was still higher in poorly-differentiated tumor areas of T3." (PMID 29396430, 2018). "CD44 activating and modulating a number of cell signaling networks that play an important role in mediating tumorigenic properties of tumor cells leading to tumor progression, metastasis and chemoresistance." (PMID 29747682, 2018). "The increased tumour growth of PC-3 cells with endogenous PLA2R1 expression in vivo could therefore indicate PLA2R1 effects in CD44+/CD24- subpopulation that require further confirmation." (PMID 30542512, 2018). "However, some authors believe the scope of CD44 expression in neoplasia is too wide to make it a useful stem cell marker." (PMID 29682524, 2018). "The knockdown of CD44 or ALK4 strongly suppressed the tumor growth in immunodeficient mice." (PMID 30061637, 2018). "The enhanced targeting to the tumor could be again a result of opsonization and interaction of HA with CD44 overexpression in cancer tissues." (PMID 29534519, 2018). "The lower CD44 expression in LDSCs may be the consequence of hypermethylation of the CD44 gene which is the case in tumor development." (PMID 30544806, 2018). "We showed that GSCs that express high levels of CD44 are present in the tumor periphery." (PMID 30210550, 2018). "CD44 is a tumor stem cell marker and is known to induce tumor stemness and metastasis." (PMID 29423071, 2018). "A number of studies validate the potential of CD44 as a therapeutic target in various tumor types." (PMID 29747682, 2018). "Because both CD44v6 and sLea are implicated in the tumor metastasis process, B3GNT3 may be involved in the possible modification of CD44 for sLea in PCSCs." (PMID 30466404, 2018). "Therefore, surgery itself was not sufficient to significantly change the expression levels of the tumor markers examined, including CD44." (PMID 30364293, 2018). "A high P/C ratio for CD44 expression in GSCs was also strongly associated with not only early tumor progression but also worse survival." (PMID 30210550, 2018). "Furthermore, the CD44+/CD49f+ population is also strongly increased among the hypoxic (EGFP+) MCF7 tumor cells." (PMID 29510720, 2018). "However, several studies have reported that circulating tumor cells from cancer patients express the HA receptor CD44 and can be captured from circulation by adhering to HA, a process that is mediated by HA receptors." (PMID 29868579, 2018). "In addition, transplanted SFCs in the brains of NOD/SCID mice generated a highly invasive tumor whose invasion front was positively stained for CD44." (PMID 30210550, 2018). "These cells sustain tumor growth and exhibit the capacity of tumoral cell differentiation, generating CD44− cells: in turn, these cells are able to restore cancer stem cell properties, reacquiring CD44 expression and self-renewing properties." (PMID 29389895, 2018).